RNVU1-17 (RNA, variant U1 small nuclear 17)
Synonyms: vU1.17; RNU1-127
Gene: Small nuclear RNA gene on chromosome 1 (143,699,456 to 143,699,619, reverse strand). Ensembl gene ENSG00000207349.
Gene Ontology:
Molecular function: pre-mRNA 5'-splice site binding
Biological process: mRNA 5'-splice site recognition
Cellular component: U1 snRNP
Homologues: Orthologues: chimpanzee U1 (99% identical), pig U1 (93% identical), rabbit U1 (93% identical), guinea pig U1 (92% identical), mouse Gm22317 (92% identical), mouse Gm24305 (92% identical), mouse Gm25679 (92% identical), mouse Gm26444 (92% identical), rat U1 (92% identical), guinea pig U1 (91% identical), rabbit U1 (91% identical), rat U1 (91% identical), and 1 more. Paralogues in human: RNU1-1 (93% identical), RNU1-2 (93% identical), RNU1-27P (93% identical), RNU1-28P (93% identical), RNU1-3 (93% identical), RNU1-4 (93% identical), RNVU1-18 (93% identical), RNVU1-28 (93% identical), RNVU1-29 (93% identical), U1 (93% identical), RNVU1-7 (93% identical), RNVU1-31 (92% identical), and 134 more.